SIRT1 (sirtuin 1)
Diseases named in the same sentence as SIRT1 in open-access papers (continued):
Sharing a sentence is not in itself a finding about the gene and the disease.
Hepatic steatosis (continued). "Therefore, regulation of SIRT1-SREBP-1c axis has been proposed as one of the underlying mechanisms linking ethanol exposure with hepatic steatosis development." (PMID 33162823, 2020). "Hepatic SIRT1 deficiency in mice impairs lipid metabolism and results in hepatic steatosis." (PMID 32230804, 2020). "Here, we report that the knocked down expression or overexpression of SIRT1 results in changes in the lipid/cholesterol (Chol) levels in the serum and liver, and causes accumulation of lipids in the liver, a process leading to hepatic steatosis." (PMID 32230804, 2020). "Indeed, SIRT1 inversely correlates with FM, and its reduction is associated with liver steatosis and increased epicardial fat thickness (EFT) in obese patients." (PMID 33202604, 2020). "Interestingly, the hepatic deficiency of SIRT1 as well as the whole body deletion of SIRT3 have been linked to increased susceptibility to hepatic steatosis and related metabolic complications." (PMID 31541116, 2019). "Moreover, the hepatic deletion of SIRT1, as well as SIRT1 downregulation, caused hepatic steatosis and inflammation." (PMID 29516009, 2018). "Oil red-O staining revealed that SIRT1-deficiency also resulted in hepatic steatosis." (PMID 29050301, 2017). "SIRT1 acts as a metabolic “switch” linked to hepatic steatosis." (PMID 26890260, 2016). "Collectively, our results indicated that the alleviation of lipid metabolism disorder and fatty liver in HFD-fed mice might be associated with the regulation of adiponectin-SIRT1-AMPK signaling." (PMID 27189109, 2016). "Indeed, we found that the deletion of ACE2 causes hepatic steatosis accompanied by an impairment of the CD36/sirtuin 1 axis, insulin signaling, and glucose metabolism in the liver." (PMID 28101297, 2016). "The expression of SIRT1 protein is also associated with protection from hepatic steatosis." (PMID 25569080, 2015). "This renders SIRT1 deficient livers more sensitive to HFD-induced hepatic steatosis." (PMID 24567900, 2014). "The nicotine adenine dinucleotide (NAD(+)−dependent protein deacetylase activation of SIRT1 is positively associated with the protection of hepatocytes against palmitate-induced lipotoxicity, and is currently emerging as a potential therapeutic target for treating fatty liver disease." (PMID 32962167, 2020). "Hepatic SIRT1 expression is reduced in different animal models of NAFLD, and loss of SIRT1 in hepatocytes leads to the development of hepatic steatosis and inflammation while on an HFD32, 33, suggesting that pharmacological activation of SIRT1 may constitute a potential therapeutic strategy." (PMID 26525891, 2015). "APE attenuated hepatic steatosis through AMPK/SIRT1-mediated regulation of lipid metabolism and effectively suppressed inflammation, oxidative stress, endoplasmic reticulum stress, and fibrotic responses." (PMID 41515160, 2025). "Collectively, these findings indicate that Hongjam alleviates hepatic steatosis by activating the SIRT1/AMPK signaling pathway, suggesting its potential as a functional food for improving metabolic dysfunction in MASLD." (PMID 41415839, 2025). "The specific deletion of hepatic Sirt1 impairs the fatty acid β-oxidation pathway, thereby heightening the susceptibility of mice to HFD-induced dyslipidemia, hepatic steatosis, inflammation, and ER stress." (PMID 40806011, 2025). "Methyl ferulate can also promote the expression of PPARα and CPT1 by upregulating SIRT1, significantly inhibiting ethanol-induced hepatic steatosis." (PMID 41154556, 2025). "Neochlorogenic acid has been shown to improve lipid profiles, hepatic steatosis, and inflammation in db/db mice with glucotoxicity, possibly by downregulating miR-34a and activating the SIRT1/AMPK pathway." (PMID 41194880, 2025). "Deletion of SIRT1 in mouse hepatocytes disrupts Lipin1 signaling and increases the Lipin1β/α ratio, resulting in inflammatory responses and exacerbating alcoholic fatty liver." (PMID 40251630, 2025).
Hepatic steatosis (continued). "For instance, IRF9 has been reported to promote the transcription of Pparα, improving hepatic steatosis or inhibiting SIRT1 activity, thus mitigating liver ischemic injury." (PMID 40083324, 2025). "This enhances AMPK activation, which in turn upregulates NAD+ biosynthesis and SIRT1 activation, an effect that has shown beneficial effects even on hepatic steatosis." (PMID 40137124, 2025). "SIRT1 was an essential member of the Sirtuin protein family and was a NAD-dependent deacetylase, closely associating with hepatic steatosis." (PMID 41223206, 2025). "The loss of SIRT1 specifically in adipose tissue impairs insulin sensitivity, whereas SIRT1 deletion in the liver results in hepatic steatosis." (PMID 40289598, 2025). "Salvianolic acid A upregulates the protein levels of phosphorylated AMPK and SIRT1 in a dose-dependent manner, improving hepatic lipotoxicity in mice with fatty liver." (PMID 41154556, 2025). "Studies also proved that HO-1 alleviates oxidative stress and reverses the adipocyte phenotype and hepatic steatosis by upregulating SIRT-1 and PPARα." (PMID 38846488, 2024). "SIRT1 has also been shown to downregulate hepatic de novo lipogenesis (DNL), while knocking out Sirt1 in the liver of mice aggravated hepatic steatosis." (PMID 39264516, 2024). "It has been reported that activation of SIRT1 enhances autophagic flux in vivo, thereby protecting osteoporosis or alleviating hepatic steatosis." (PMID 38790630, 2024). "In conclusion, the present study revealed that 8PG is a novel AMPK activator from CGJ and is associated with inhibiting lipid accumulation and enhancing β-oxidation through the SIRT1-mediated pathway, thereby attenuating hepatic steatosis." (PMID 39273677, 2024). "The longevity-related factor SIRT1 has also been found to downregulate hepatic DNL, and liver specific Sirt1 knockout mice manifested hepatic steatosis." (PMID 39264516, 2024). "Consistent with these actions, heterozygous SIRT1 knockout (Sirt1+/−) mice fed an HFD exhibit hepatic steatosis with significant increases in lipid content and liver inflammation." (PMID 38807218, 2024). "Actually, it has previously been reported that Garcinia mangostana and its bioactive compounds suppress hepatic steatosis through Sirtuin1 (Sirt1)-AMPK in high-fat-diet-induced obese mice." (PMID 39335940, 2024). "Previous reports have shown that Momordica charantia enhances liver FGF21 and AMPK/Sirt1 signaling to alleviate hepatic steatosis in mice." (PMID 38644407, 2024). "Resveratrol supplementation decreases inflammation while minimizing hepatic steatosis via activation of the AMPKα-SIRT1 pathway, suppressing the nuclear factor kappa B (NF-κB) inflammatory pathway." (PMID 38612556, 2024). "In contrast, hepatic SIRT1 overexpression in mice protects against high fat diet-induced hepatic steatosis." (PMID 38543036, 2024). "Liver-specific SIRT1 knockout mice fed a high-fat Western diet display impaired lipid metabolism and hepatic steatosis, inflammation, and endoplasmic reticulum stress." (PMID 38543036, 2024). "Overall, these findings indicate that SIRT1 activation contributes to the prevention of ER stress-induced fatty liver by VLDLR levels and modulating the serum and hepatic levels of triglycerides." (PMID 38807218, 2024). "Accumulating evidence indicates that the NLRP3 inflammasome signaling pathway is involved in the progression of hepatic steatosis to NASH through SIRT1." (PMID 38543036, 2024). "Other study demonstrated that short-term DHA supplementation decreases hepatic steatosis and upregulates Sirt1 mRNA and protein expression in the liver of middle-aged HFD-induced MASLD mice model." (PMID 39264516, 2024). "The favorable effect of 1,25(OH)2D on hepatic steatosis and inflammation, at least in part through SIRT1 in AML-12 mouse hepatocytes." (PMID 38543036, 2024). "The imbalance between fatty acid oxidation and lipogenesis due to decreased SIRT1 activity in T2DM can lead to hepatic steatosis." (PMID 39796441, 2024).
Hepatic steatosis (continued). "During the development of fatty liver, several stimuli such as fructose consumption reduce hepatic SIRT1 levels, exacerbating this condition by increasing VLDLR levels and the subsequent delivery of triglyceride-rich lipoproteins to the liver." (PMID 38807218, 2024). "Overall, 8PG acts as a potent AMPK activator, further attenuating hepatic steatosis via the SIRT1-mediated pathway and providing new avenues for dietary interventions to treat metabolic dysfunction-associated steatotic liver disease (MASLD)." (PMID 39273677, 2024). "One of the important findings of the present study was the potential involvement of the miR-34a/SIRT1 axis in the induction of liver steatosis following exposure to dust and undergoing IR injury." (PMID 36742142, 2023). "As a result, it can be concluded that Que-metformin improves hepatic steatosis via SIRT1-dependent autophagy induction in HepG2 cells." (PMID 38116565, 2023). "In summary, an in vitro study indicated that E2 treatment alleviated LA-induced hepatic steatosis by upregulating the ERα/SIRT1/PCG-1α pathway." (PMID 38136219, 2023). "The Sirt1 inhibitor Ex527 blocked the protective effect of E2 on decreasing TG accumulation, relieving lipid peroxidation and mitigating LA-induced hepatic steatosis." (PMID 38136219, 2023). "RES is a potent SIRT1 agonist, while AMPK has been shown to be closely associated with insulin resistance and hepatic steatosis." (PMID 36229407, 2023). "Second, our results indicated that ATF6 promote SIRT1 signal and regulate the inflammatory response in liver steatosis." (PMID 38007457, 2023). "Liver-specific Sirt1 knockout mice are prone to hepatic steatosis, endoplasmic reticulum stress, and liver inflammation; by contrast, overexpression of SIRT1 alleviates hepatic steatosis in high-fat-diet (HFD)-induced mice." (PMID 37367070, 2023). "RSV alleviated HFD-induced hepatic steatosis in mice liver and reduced lipid droplet accumulation in a SIRT1/ATF6-dependent manner." (PMID 37834101, 2023). "In diet-induced and genetically obese mice, pharmacological SIRT1 activators suppressed the hepatic lipid and cholesterol levels as well as liver steatosis." (PMID 37834101, 2023). "Sirtuin 1 (SIRT1) activation attenuated hepatic steatosis and inflammation in HFD-induced NAFLD by inhibiting CD38 expression and NF-κB signaling pathway 24-26." (PMID 36794157, 2023). "Inhibition of Nampt aggravated HFD-induced hepatic steatosis, lipid accumulation, and oxidative stress in mice through regulating SIRT1 signaling pathway." (PMID 36831235, 2023). "Celastrol supplementation is shown to ameliorate HFD-induced hepatic steatosis in mice by increasing hepatic SIRT1." (PMID 37189351, 2023). "The findings of this study demonstrated, for the first time, that the combination of Que and metformin relieved hepatic steatosis by stimulating autophagy through the cAMP/AMPK/SIRT1 pathway." (PMID 38116565, 2023). "Prior investigation has verified a reduction in SIRT1 expression in the model of TAM-induced hepatic steatosis in high-fat-fed rats." (PMID 37934372, 2023). "RES weakens hepatic steatosis and lipid metabolic disorder in KKAy mice, possibly by up‐regulating SIRT1 expression and the phosphorylation of AMPK." (PMID 36229407, 2023). "Our studies identify SIRT1 as an endogenous regulator of the fibroblast growth factor 21 (FGF21) hepatocyte‐derived hormone FGF21 which reduces hepatic steatosis and increases energy expenditure in young mice." (PMID 36999514, 2023). "Previous authors reported that the SIRT-1 /autophagy pathway is crucial as the protective effects of resveratrol against HFD -induced hepatic steatosis." (PMID 36991247, 2023). "Previous studies have reported that SIRT1 by deacetylating the proteins involved in the regulation of lipogenesis and fatty acid oxidation is involved in hepatic steatosis." (PMID 36742142, 2023).
Hepatic steatosis (continued). "In the constructed zebrafish model of NAFLD, swimming exercise improved hepatic steatosis, inflammation, fibrosis and so on caused by HFD, and these beneficial effects were related to activated Sirt1 signaling." (PMID 36882837, 2023). "A previous study has indicated that the deacetylating effect of SIRT1 on histone improves hepatic steatosis." (PMID 37190114, 2023). "What is more, studies have provided a new finding that apart from regulating SIRT3, the activation of SIRT1 also participates in the DMY treatment of fatty liver disease." (PMID 36229407, 2023). "Sirtuin 1(SIRT1) is a nicotinamide adenine dinucleotide (NAD+, NADH)-dependent class III histone deacetylase, and its role in alcohol-associated fatty liver disease has been well documented." (PMID 37892472, 2023). "SIRT1 is another regulator of hepatic lipid homeostasis, and it plays an important role in hepatic steatosis." (PMID 36432495, 2022). "Obese mice with metformin treatment showed improved hepatic steatosis with upregulation of SIRT1 expression and LC3-II level." (PMID 35909524, 2022). "The involvement of the SIRT1/PPARα/PGC-1α axis in lycopene’s mode of action, with a specific focus on hepatic steatosis and glucose metabolism, was confirmed in mice that over-expressed SIRT-1 and were fed with HFD." (PMID 35883529, 2022). "Rats treated with resveratrol not only showed partial prevention of hepatic steatosis symptoms with increased SIRT1 and autophagy markers level, but also decreased energy intake and body weight." (PMID 35909524, 2022). "In the context of NASH, systematic SIRT1 ablation or hepatocyte SIRT1 deletion led to hepatic steatosis and inflammation, and SIRT1 overexpression protected against diet-induced steatosis." (PMID 35855331, 2022). "Another study reported that tomato powder (rich in β-carotene) inhibits hepatic steatosis and inflammation potentially through restoring sirturin 1 (SIRT1) activity and adiponectin function." (PMID 36109506, 2022). "Compared to control, both rapamycin (autophagy inhibitor) and SRT1720 (SIRT1 activator) showed significant improvement in hepatic steatosis condition of high-fat diet mice." (PMID 35909524, 2022). "More specifically, the antagonistic relationship between SIRT1 and NF-κB seems to be protective against hepatic steatosis and the metabolic energy balance under hypothalamic control." (PMID 35956321, 2022). "In several studies, the beneficial effects of SIRT1 activation against fatty liver disease have been verified." (PMID 36296907, 2022). "Meanwhile, SIRT1 has been demonstrated to have a significant biological effect in regulating lipid metabolism, oxidative stress, and inflammation in the liver as fatty liver disease progresses." (PMID 36443854, 2022). "In vivo studies on transgenic mice, with the deletion of exon 4 in the SIRT1 gene, showed an increased rate of hepatic steatosis when fed with a high-fat diet." (PMID 35055159, 2022). "In the current study, we found that metformin still effectively alleviated HFD-induced hepatic steatosis in Sirt1+/− mice." (PMID 34483906, 2021). "This is first time that dietary betaine has been reported to operate through modulating Sirt1 to regulate lipid metabolic pathways (Pparɑ and Srebp-1) in a teleost, consequently alleviating lipid metabolism disorders and attenuate hepatic steatosis." (PMID 34248992, 2021). "It has been reported that deletion of Sirt1 in hepatocytes resulted in hepatic steatosis and inflammation 26, indicating that Sirt1 played an important role in NAFLD." (PMID 34803499, 2021). "This suggests that Grail aggravates the progression of hepatic steatosis by inhibiting the function of Sirt1." (PMID 33771967, 2021). "Activation of SIRT1 protects against metabolic damage induced by a high-fat diet, along with improved glucose tolerance and protection against hepatic steatosis." (PMID 33609766, 2021).
Hepatic steatosis (continued). "SIRT1 overexpression improved effects on HFD-induced fatty liver and pro-inflammatory cytokines via downregulation of NF-κB activity." (PMID 34483906, 2021). "In conclusion, the present study has provided further insight into the mechanisms of betaine attenuation of high-fat diet-induced hepatic steatosis and inflammatory responses through modulating the Sirt1/Srebp-1/Pparɑ pathway." (PMID 34248992, 2021). "SIRT1 regulates the expression of ChREBP protein, as demonstrated by the upregulation of ChREBP in specific SIRT1 knockout mice, which led to imbalance of lipid utilization and lipid excretion, accompanied by severe hepatic steatosis." (PMID 33994911, 2021). "In mice with HFD-induced obesity, maslinic acid was reported to protect against hepatic steatosis through regulation of the Sirt1/AMPK signaling pathway." (PMID 34344394, 2021). "Aside from autophagy, liver-specific SIRT1 knockout mice challenged with HFD developed hepatic steatosis, inflammation and endoplasmic reticulum stress." (PMID 34850865, 2021). "Several studies showed that overexpression of SIRT1 and NR helps restore diet-induced hepatic steatosis and mitochondrial dysfunction by elevating NAD+ levels." (PMID 33609766, 2021). "The inhibition of PARP-1 can increase NAD+ content and SIRT1 activity, enhance lipid metabolism, and improve hepatic steatosis in hepatocytes under oxidative stress and mice fed a high-fat diet." (PMID 34393826, 2021). "Resveratrol improves hepatic steatosis by mediating the Sirt1/activating transcription factor 6 dependent mechanism." (PMID 34684653, 2021). "The possibility for this is that SIRT1 only partly mediates metformin-improved hepatic steatosis by regulating de novo lipogenesis, similar to AMPK." (PMID 34483906, 2021). "SIRT1 plays a beneficial role in modulating hepatic lipid metabolism, and the activation of SIRT1 hinders the progression of fatty liver diseases." (PMID 34681600, 2021). "RSV additionally prevented the formation of hepatic steatosis in C57BL/6 mice infected with recombinant core HCV adenoviruses by inhibiting the expression of SIRT1 and PPAR-α (peroxisome proliferator-activated receptor-α)." (PMID 33805795, 2021). "Hepatocyte-specific deletion of SIRT1 disturbs PGC-1α-PPARα signaling pathway, reduces fatty acid oxidation, and causes aggravated liver steatosis and inflammation." (PMID 33162823, 2020). "In response to nutrients, GLP-1RAs were also found to alleviate liver steatosis through the upregulation of SIRT1 expression, activating the AMPK pathway and inhibiting SREBP-1c expression." (PMID 33330497, 2020). "Resveratrol can be considered as a pharmacological SIRT1 activator and take effects on hepatic steatosis by improving lipid-related gene transcriptional expression, oxidative stress and inflammation, meanwhile decreasing ER stress via the autophagy." (PMID 32477116, 2020). "Our findings are in agreement with previous studies showing that LBP enhanced SIRT1 expression in hypoxic pulmonary vascular smooth muscle cells and in high-fat-diet-induced hepatic steatosis." (PMID 32362869, 2020). "In the HepG2 cell model of hepatic steatosis, the miR-141 overexpression reduced cell survival through targeting the SIRT1/AMPK pathway." (PMID 33204711, 2020). "In summary, the present study suggests that the low dose of SMSP (50 mg/kg) effectively reduced the hepatic steatosis through the activation of SIRT1/AMPK-mediated signaling cascades in ethanol-treated rats." (PMID 32143357, 2020). "Resveratrol is considered to be a Sirt1 enhancer, and obese mice treated with resveratrol have improved NAFLD and liver steatosis via promotion of the Sirt1/AMPK pathway." (PMID 33014333, 2020). "In the present study, our results showed that hepatic steatosis decreased SIRT1 activity that facilitated hepatic fatty acid synthesis and inhibited fatty acid oxidation and lipid transport." (PMID 32230804, 2020).